CD24 (CD24 molecule)
Diseases named in the same sentence as CD24 in open-access papers (continued):
Sharing a sentence is not in itself a finding about the gene and the disease.
triple-negative breast carcinoma (44 papers, 2011 to 2025). An invasive breast carcinoma which is negative for expression of estrogen receptor (ER), progesterone receptor (PR), and human epidermal growth factor receptor 2 (HER2). "Importantly, multivariate analysis that included tumour size, lymph node metastasis and chemotherapy demonstrated that high CD24 expression is independently associated with poorer survival in luminal A and triple-negative breast cancer (TNBC) subtypes." (PMID 26444008, 2015). "Specific CAR-T cells targeting CD24 have been shown to exhibit significant anti-tumor activity and hold potential for use in the treatment of triple-negative breast cancer." (PMID 39596658, 2024). "Remarkably, comparing with luminal and HER2 phenotypes, triple negative breast cancer (TNBC) has abundance of CD44 + /CD24- stem cells, due to their potent self-renewal and differentiation capacities." (PMID 37919766, 2023). "Short-term Olaparib treatment has also been previously demonstrated to induce cancer cell invasion and enrich PD-L1 and CD44+CD24– stemness marker levels in triple-negative breast cancer (TNBC) cell lines." (PMID 34956861, 2021). "Here we used the biomarker combination of ALDH and CD24/CD44 to sort four populations isolated from triple-negative breast cancer (TNBC) patient-derived xenografts, and performed whole-transcriptome sequencing on each population." (PMID 29471829, 2018). "Triple-negative breast cancer (TNBC) is an aggressive tumor subtype with an enriched CD44+/CD24- stem-like population." (PMID 26528725, 2015). "Our previous work on triple-negative breast cancer (TNBC) revealed the involvement of CD24 in TNBC progression and metastatic lung colonization via enhancing anoikis resistance and angiogenesis through receptor tyrosine kinase (RTK) oncogenic pathways such as EGFR and MET." (PMID 40783744, 2025). "The expression of CD24 in triple-negative breast cancer could help the cancer cells achieve the immune evasion through CD24-Siglec-10 signaling to inhibit the function of Tumor-associated macrophages (TAMs)." (PMID 37359556, 2023). "In ovarian and triple-negative breast cancers, CD24 signaling could serve as a target for cancer immunotherapy through enhancing tumor-associated macrophage expression of Siglec-10." (PMID 35037689, 2022). "Previous studies have shown that CD44+/CD24- breast CSCs may be a dominant factor for the relapse of triple negative breast cancer (TNBC), due to their potent self-renewal and differentiation capacities." (PMID 34318746, 2021). "The results of CD44/CD24 staining in two of the triple-negative breast cancer cell lines tested (MCF10AT and MCF10CA1α) indicated an overall increase in mesenchymal-like CSC population after treatment with Efavirenz, opposite to the results obtained for epithelial-like CSCs." (PMID 34944852, 2021). "We used a combination of CD44, CD24 and EpCam markers to isolate CSCs since previous works have shown that these markers identify a subpopulation with increased tumor-initiating capabilities in triple-negative breast cancer cell lines." (PMID 32183150, 2020). "Previous studies suggest that CD44+/CD24- cells, subpopulation of cancer stem cells with self-renewing and tumor-initiating capacities, are partly responsible for chemoresistance and therapeutic failure of triple negative breast cancer." (PMID 29190901, 2017). "Interestingly, inhibition of Cdk2 kinase activity selectively targets and restores the chemosensitivity of SUM149PT in a CD44+/CD24-/Low stem-like subpopulation of triple-negative breast cancer cells." (PMID 25605243, 2015). "Sphere culture significantly enriched the subpopulation of CD44+/CD24−/low/EpCAM+ cells, supporting the hypothesis that CD44+/CD24−/low/EpCAM+ cells are a more selective cancer stem cell subpopulation than CD44+/CD24−/low cells in triple-negative breast cancer." (PMID 25229616, 2014).
triple-negative breast carcinoma (continued). "Here, we investigated the role of CD24a, the murine CD24 gene, in tumor progression and TME immune dynamics in a murine triple-negative breast cancer (TNBC) model." (PMID 40783744, 2025). "Recently, in triple-negative breast cancer cells MDA-MB-321, its activity was related to the decrease in CD44, CD24, Bcl2, release of Cytochrome c to the cytoplasm, and mitochondrial reduction." (PMID 38255214, 2024). "The significance of direct interactions of GRP78 (and HSP90α) with PRDM14 for the maintenance of CSC-like populations of CD24(−)/CD44(+) cells and drug-resistant SP cells has been demonstrated in a model of triple-negative breast cancer." (PMID 32268506, 2020). "In conclusion, we demonstrated the inhibitory effects of CDDO-Im on triple-negative breast cancer with a potential to target cancer stem cell subpopulation, as evidenced by inhibition of CD44+/CD24−/low/EpCAM+ cells and tumorsphere formation." (PMID 25229616, 2014). "Triple-negative breast cancer (TNBC) high rate of relapse is thought to be due to the presence of tumor-initiating cells (TICs), molecularly defined as being CD44high/CD24-/low." (PMID 22309939, 2012). "We have shown that compound 1 lowers CSC, CD44+CD24+, and CD44− subpopulations and expression of CD15s in CD44+CD24+ and CD44− cells, showing that it or similar analogs could be developed into new treatments for triple-negative breast cancer." (PMID 34206154, 2021). "We have shown that compound 1 lowers CSC, CD44+CD24+, and CD44− subpopulations and expression of CD15s in CD44+CD24+ and CD44− cells, showing that it or similar analogues could be developed into new treatments for triple-negative breast cancer." (PMID 34206154, 2021). "Treatment with CDDO-Im significantly decreased the number of CD44+/CD24−/low/EpCAM+ cells in sphere culture, suggesting that CDDO-Im could be used as a potential agent to target cancer stem cells in triple negative breast cancer." (PMID 25229616, 2014). "Besides, BCSCs expressing both CD24- CD44+ and ALDH+ were related with worse progression-free survival (PFS) and could serve as an independent prognostic factor in some subgroups of triple negative breast cancer." (PMID 34801088, 2021).
liver cancer (41 papers, 2014 to 2025). An epithelial or non-epithelial malignant neoplasm that arises from the liver. "Recent studies have shown that CD24 is overexpressed in various human tumors, including liver cancer, thyroid cancer, and esophageal cancer, where it plays a crucial role in tumor initiation, progression, invasion, and metastasis." (PMID 41195275, 2025). "A drug conjugate of nitric oxide (NO) with anti-CD24 antibodies can selectively and efficiently inhibit liver cancer." (PMID 40486886, 2025). "The trial noted elevated expression of CD24 in primary liver cancer and incorporated CD24 peptides into the treatment protocol." (PMID 40486886, 2025). "SENP1 overexpression increases CD24+ cell population and upregulates stemness-related genes expression in liver cancer cells." (PMID 38389923, 2024). "Novel antibodies like G7 mAb have been developed to target liver cancer stem cells specifically, demonstrating the potential of CD24-targeting strategies." (PMID 38881902, 2024). "Studies have shown that CD24 is widely expressed in various malignant tumors such as gastric cancer, ovarian cancer, liver cancer and lung cancer." (PMID 38914670, 2024). "Studies have shown that the abnormal expression of CD24 has promoted the proliferation, migration and invasion of liver cancer cells." (PMID 38914670, 2024). "They used molecular biology techniques to knock down CD24 expression in drug-resistant cells, and the cells were sensitive to sorafenib treatment, indicating that CD24 had a unique role in the phenomenon of DR in liver cancer cells." (PMID 37077416, 2023). "have shown that the CD24 antibody G7S has a high specific affinity for the CD24 protein of liver cancer cells, so we chose this sequence as the CD24 antibody sequence for the next experiment." (PMID 36866919, 2023). "Our results have demonstrated that CD24, a “don’t eat me” signal, has been upregulated in liver cancer organoids together with BNIP3." (PMID 35912211, 2022). "First, the expression levels of liver cancer-associated markers, AFP, GPC3 and CK19 as well as liver CSC markers, CD44, CD24 and CD133, in malignant tumours were relatively high compared to that in normal liver by RT-qPCR." (PMID 32203212, 2020). "Lee and coworkers identified CD24, a mucin-like cell surface glycoprotein as marker of liver cancer stem cells." (PMID 28930164, 2017). "These consistent findings across experimental and bioinformatic approaches suggest that CD24 upregulation is particularly prominent in C. sinensis-associated HCC and could be crucial in the development of liver cancer and the advancement of tumors." (PMID 40830893, 2025). "Preclinical studies and clinical trials have shown that targeting CD24 can significantly reduce lung metastases in bladder cancer and target liver cancer stem cells, highlighting its role in the development of metastases and its necessity for the proliferation of certain cancer cells." (PMID 38881902, 2024). "CD24 was highly expressed in sorafenib-resistant liver cancer cells, suggesting that it might be a potential target for HCC treatment." (PMID 35127582, 2022). "Interestingly, liver cancer cells cultured as organoids have a significantly upregulated CD24 expression (p < 0.05), which played important roles in evasion from phagocytosis of cancer cells from macrophages." (PMID 35912211, 2022). "To further confirm that the miPS-Huh7cmP1 cells were enriched with the cells expressing liver cancer-associated markers (AFP, GPC3 and CK19) and CSC markers (CD44, CD133 and CD24), we examined the gene expression levels compared to those in miPSCs and miPS-Huh7cm cells." (PMID 32203212, 2020). "ADCs containing GPC3 or CD24 antibodies may provide a more accurate and effective way of treating liver cancer, especially when systemic therapy is combined with locoregional trans-arterial administration directly into the vicinity of the HCC." (PMID 32575828, 2020).
liver cancer (continued). "Our previous results have proved that CD24 was a specific marker of liver cancer stem cells." (PMID 33324558, 2020). "CD24 expression levels are also related to liver cancer progression and prognosis." (PMID 29844385, 2018). "Collectively, these results suggest that CsESPs upregulate CD24 expression via transcriptional regulation of E2F1, thereby promoting proliferation and inhibiting apoptosis in liver cancer cells." (PMID 40830893, 2025). "The expression of liver cancer stem cell markers (ICAM1, CD47, CD24 and EPCAM) in HCC cells were determined by qPCR." (PMID 38169544, 2024). "Immuno-reactive liver cancer markers AFP, GPC3 and CK19 were positively stained as well as the CSC markers such as CD44, CD24 and CD133 in the tumour tissue developed in the liver." (PMID 32203212, 2020). "We used CD133/CD44/CD24/EpCAM MicroBeads to isolate hLCSCs from human liver cancer cell line Huh7 by detecting the markers of hLCSCs, including CD133, CD44, CD24 and EpCAM." (PMID 29602239, 2018). "A number of markers, including CD13, CD44, CD24, CD90, CD133, EpCAM, DLK1, ALDH1 can be used to identify liver cancer stem cells." (PMID 28930164, 2017). "Our results demonstrated that ectopic expression of CD90 induced the expression of liver cancer stem cell markers, including CD133, CD24, and EpCAM." (PMID 26556861, 2015). "In the isolated cells from human liver cancer cell line Huh7, Cells with CD133+/CD44+/CD24+/EpCAM+(HLCSC) was 15.3 ± 5.26%, Cells with CD133−/CD44−/CD24−/EpCAM-(non-HLCSC) was 5.23 ± 2.56% and others was 79.43 ± 5.19% (P < 0.01, respectively)." (PMID 26513297, 2015). "Liver CSC markers include EpCAM, CD133, CD90, CD44, CD24, CD13, and OV6, some of these markers are considered functional with highly invasive, metastasis, chemotherapy resistant of liver cancer." (PMID 26540347, 2015). "To compare the growth and gene expression between liver cancer stem cell and unstemic liver cancer cells, we isolated the liver cancer stem cells from human liver cancer cell line Huh7 by CD133/CD44/CD24/EpCAM MicroBead according to the schematic digram." (PMID 26513297, 2015). "Hepatic cancer stem cells have been identified by several markers, including EpCAM, CD90, CD133, CD44, CD24, and CD13." (PMID 26556861, 2015). "Thus, we clustered the cell populations into three groups with 3_Positive (CD24+EPCAM+CD133+) LCSCs, 3_Negative (CD24−EPCAM−CD133−) liver cancer cells and other cells, respectively." (PMID 37466793, 2023). "We found that BJJP significantly reduced the expressions of CD24, CD133 and EpCAM in the liver cancer tissues, indicating BJJP could suppress the properties of CSCs in HCC." (PMID 34297271, 2022). "CD90 expresses on the liver tumor islands or parenchymal, instead of the stroma, and there is co-expression of CD90 with CD24 and CD133 just on CD90+ liver cancer cells and not on other cells." (PMID 27332878, 2016). "Western blotting showed that liver cancer stem cells CD133, CD44, CD24 and EpCAM were expressed in human liver cancer stem cells(HLCSC), as well as CD133, CD44, CD24 and EpCAM were not expressed in liver cancer unstem cells (non-HLCSC)." (PMID 26513297, 2015).
gastric cancer (36 papers, 2008 to 2025). A primary or metastatic malignant neoplasm involving the stomach. "The positivity of CD24 is associated with tumor progression, invasion, lymphatic metastasis, and, consequently, a dismal prognosis in both Lauren types of gastric cancer." (PMID 36846589, 2023). "CD24, a mucin-like membrane glycoprotein, plays a critical role in carcinogenesis, but its role in human gastric cancer and the underlying mechanism remains undefined." (PMID 26830684, 2016). "Analysis of gastric cancer specimens revealed a positive correlation between CD24 and EGFR levels and an association between CD24 expression and worse prognosis." (PMID 26830684, 2016). "CD24 overexpression in patients with gastric cancer indicated worse survival outcomes and was associated with common clinicopathological poor prognostic factors." (PMID 25503963, 2014). "This small retrospective series served as an initial study to investigate the potential association between CD44 and CD24 and gastric cancer recurrence, but a study with a larger sample is needed to confirm our preliminary results." (PMID 22839505, 2012). "Overexpression of CD24 was observed in gastric cancer tissue and was associated with increased lymph node metastasis and venous invasion of cancer cells, and CD24 was shown to directly affect gastric cancer cell motility and invasive capability." (PMID 26830684, 2016). "A cohort study and flow cytometry analysis of 127 gastric cancer patients showed that CD24+CD44+CD54+ EpCAM+ cells were positively correlated with tumour metastasis and were present in untreated patients." (PMID 40665579, 2025). "A cohort study of 127 untreated gastric cancer patients demonstrated that CD24+CD44+CD54+EpCAM+ cells are bona fide gastric CSCs." (PMID 40665579, 2025). "In our group, we identified a gastric cancer stem cell (GCSC) subpopulation with the CD24+CD44+CD326+ICAM1+ immunophenotype in patients with gastric cancer." (PMID 39201551, 2024). "Immunofluorescence staining confirmed the presence of CD44 and CD24 proteins on the surface of gastric cancer cells, showing that increased ACAT1 levels suppress CD44 expression and enhance CD24 expression." (PMID 39247186, 2024). "The expression of CD44 and OCT4 was decreased, while CD24 expression was increased by overexpressing ACAT1 in MKN45 gastric cancer cells." (PMID 39247186, 2024). "Previously, we described the presence of gastric cancer stem cells with the immunophenotype CD24+CD44+CD326+ICAM1+ in the gastric tissue of gastric cancer patients and some cell lines, including AGS." (PMID 39201551, 2024). "Our research group identified gastric cancer stem cells (GCSCs) with the CD24+CD44+CD326+ICAM1+ immunophenotype isolated from gastric cancer patients." (PMID 39201551, 2024). "Previously, our research group reported a GCSC immunophenotype (CD24+CD44+CD326+ICAM1+) in gastric cancer patients." (PMID 39201551, 2024). "Ultimately, under our conditions, we conclude that CD24+CD44+CD54+EpCAM+ cells are true gastric cancer stem cells (GCSCs)." (PMID 36737794, 2023). "Gastric cancer stemness can be determined by investigating the expression of cell surface markers, namely CD24, CD44, and LGR5, and stemness-related transcriptional factors, namely Nanog and SOX2." (PMID 35740372, 2022). "Hypoxia inducible factor (HIF) can bind to the promoter of CD24, thereby promoting the invasion and metastasis of gastric cancer cells." (PMID 29844385, 2018). "Since there are no consensus cell surface markers for putative cancer stem cells in gastric cancer, we examined changes in the following markers: CD24, CD33, CD44, CD90 and CD133 that are reported in the literature." (PMID 28404967, 2017). "We here show that CD24 positively regulates the expression of EGFR in gastric cancer cells, and that expression of CD24 supports the EGFR-PI3 K/Akt and EGFR-ERK signaling pathway." (PMID 26830684, 2016).